MLANA (melan-A)
Diseases named in the same sentence as MLANA in open-access papers (continued):
Sharing a sentence is not in itself a finding about the gene and the disease.
melanoma (continued). "Melanoma cells from freshly disrupted spheroids indeed induced IFN-γ secretion in Melan-A/MART-127–35-specific CTL clones to levels intermediate between those induced by 2D or 3D cultured HBL." (PMID 17342088, 2007). "The second model is also relevant to clinical immunotherapy, with the use of A02 human melanoma cells as the target and a Melan-A/MART-1-specific cytotoxic T-lymphocyte (CTL) clone as effector cells." (PMID 17311012, 2007). "It has been recently reported that OSM, produced by melanoma cells actively downregulates Melan-A/MART-1 mRNA transcription inducing antigen silencing in tumour cells." (PMID 17342088, 2007). "The HLA class I haplotype of the patient was A2.A26.B35.B44 and the initial tumor sites expressed both MAGE1, MAGE3 and other melanoma antigens such as Melan-A/MART1 and NA-17 (as assessed using semiquantitative RT-PCR)." (PMID 15740633, 2005). "HLA-A2.1+, Melan-A/MART-1-NA-8 melanoma cells served as targets of specific CTL in 51Cr release assays upon pulsing by untreated or human plasma-treated soluble or SSL-encapsulated Melan-A/MART-1 27–35 (M27–35) or 26–35 (M26–35) epitopes." (PMID 14710238, 2004). "Among TAA groups are the differentiation antigens, such as Tyrosinase, gp100 and MART1/Melan-A in melanoma, and PSA in prostate carcinoma." (PMID 15213716, 2004). "In response to targeted HLA-A2/Melan A complexes greater than three-fold increases in tetramer positive cells were seen in three of four volunteers and in one of the melanoma patients." (PMID 11953895, 2002). "Diagnosis was established based on morphology and strong nuclear TFE3 immunoreactivity, supported by additional immunohistochemical (IHC) markers including cluster of differentiation 10 (CD10), Melan-A, human melanoma black 45 (HMB45), vimentin, carbonic anhydrase IX (CAIX), and cytokeratins." (PMID 42220779, 2026). "HMB-45, Melan-A, and S-100 are specific markers of melanoma." (PMID 41536409, 2025). "Similarly, Mlana (melan-A), which is specifically expressed in melanocytes, melanomas, and retinal pigment epithelial cells, plays a pivotal role in melanocyte differentiation under the guidance of the Mitf gene." (PMID 40745198, 2025). "Melanoma dedifferentiation refers to the tumor's progression toward a less differentiated state, often including the loss of typical melanocytic markers such as S100 protein, SOX10, Melan-A, and HMB-45." (PMID 40125165, 2025). "The lesion lacked precursor melanoma and showed a loss of Melan-A expression, with preservation of SOX10 expression." (PMID 40125165, 2025). "Notably, PAX3 was significantly upregulated in conjunctival/limbal melanoma tissues compared to healthy counterparts, with expression co-localizing with melanocyte markers (Melan-A, HMB45, SOX10) and the proliferation marker Ki-67 in melanoma cells." (PMID 40216818, 2025). "Double immunofluorescence staining of conjunctival melanoma paraffin sections demonstrated that all PAX3+ cells (green, arrows) co-expressed the melanocyte marker Melan-A (red), and the intensity of Melan-A staining was notably higher in the melanoma tissues relative to healthy tissues." (PMID 40216818, 2025). "Notably, Melan-A-specific CD8+ T cells in melanoma patients exhibit a naïve phenotype (CCR7+CD45RA+), a trait also observed in CD8+ T cells from cancer-free lymph nodes in this group." (PMID 40136652, 2025). "Importantly, the PDO cultures displayed stability in their melanoma immunohistochemistry markers, maintaining positive staining for S100 and Melan A even after multiple passages." (PMID 39204387, 2024). "For instance, benign granular cell tumors are positive for S-100 protein, CD63, CD68 and neuron-specific enolase whereas atypical fibroxanthoma stains negatively for S100 protein, Melan-A, human melanoma black (HMB)-45 pan-cytokeratin (CK) and actin and positively for CD68 and vimentin." (PMID 36832159, 2023).
melanoma (continued). "Especially to A*02/MLANAELA, derived from the melanoma antigen recognized by T cells 1 (known as MART1 or MLANA) in patients #2 and #6, which showed specific TCRs in blood, oWAT, but especially in sWAT, occupying 21.1% and 10.7% of the sequenced sWAT repertoire, respectively." (PMID 38053998, 2023). "According with our hypothesis, immunofluorescence analysis with specific labeling for melanoma cells (anti-Melan-A staining) revealed that the area covered by TG2 KO experimental metastasis in the lungs are larger than those formed after injection of WT cells." (PMID 37898636, 2023). "MLANA and tyrosinase have been proposed as biomarkers for melanoma detection." (PMID 36614248, 2023). "In an exploratory analysis of the phase III trial EORTC 18991, which compared adjuvant pegylated interferon-alpha-2b with surveillance in patients with resected stage III melanoma, the presence of mCTCs was verified using RT-PCR for tyrosinase and Mart-1/Melan-A transcripts." (PMID 38201222, 2023). "Furthermore, the concomitant use of Melan-A with markers such as HMB-45 or S-100 was also recommended in order to avoid the misdiagnosing of “pseudomelanocytic” cells as melanoma cells." (PMID 36980327, 2023). "By taking advantage of a panel of CD8+ Ag-specific (Melan-A+ or gp100+) T-cell clones isolated from the peripheral blood of melanoma patients, we recently reported that the inhibitory effect of PD1 is associated with the co-expression of CD28, consistent with earlier studies." (PMID 37898752, 2023). "Reactive T cells against MLANA appear in some pathological contexts, such as vitiligo and melanoma." (PMID 38053998, 2023). "Because of the observed Melan-A expression in IHC we researched for melanoma-specific genomic aberrations as high tumor mutational burden (TMB), UV-associated mutational signature and characteristic melanoma driver mutations." (PMID 35501497, 2023). "To detect the spectrum of responsiveness of endogenous, tumor-primed CD8 T cells towards epitope variants with different Ki affinities for HLA, we generated 10 Melan-A/MART-126-35-specific T cell clones derived from TILNs of 3 patients with spontaneous immunological responses toward their melanoma." (PMID 36032094, 2022). "Therefore, an immunodetection was performed using a mouse monoclonal specific antibody against Melan-A, also known as Melanoma antigen recognized by T-cells (MART-1), responsible for triggering the synthesis of melanin inclusions." (PMID 36411485, 2022). "Interestingly, levels of HMB-45 are lower in metastatic melanoma compared to primary lesions, and its specificity is lower for malignant melanoma in sentinel lymph nodes compared to other markers, such as Melan-A." (PMID 35565234, 2022). "Similarly, antigen-specific T cells (Melan-A/MART-1) extracted from metastases of melanoma patients exhibit increased levels of LAG-3 and other IRs (CTLA4, TIM3) compared with the expression on peripheral blood lymphocytes." (PMID 36077354, 2022). "Melanoma clinical trials have also shown that targeting Melan-A-specific CD8+ CTL cells could effectively alleviate patient conditions." (PMID 35725570, 2022). "Metastatic carcinomas would be Keratin positive, while melanomas positive for Melan-A, HMB-45, and diffusely positive for S100 with immunochemistry (in contrast to the paragangliomas, where only the sustentacular cells are highlighted with the S100 immunostaining)." (PMID 36010170, 2022). "Tissue staining with Melan A and S100 confirmed that the tumors were human melanoma-derived." (PMID 34880267, 2021). "The eye enucleation was performed because of a Melan-A-positive melanoma in the choroid." (PMID 34502238, 2021). "TNFα also promotes melanoma dedifferentiation by suppressing the expression of the microphthalmia-associated transcription factor (MITF), a master regulator of the pigmentation pathway and melanocytic antigens, including the TRP1, DCT and MLANA genes." (PMID 34073253, 2021).
melanoma (continued). "Indeed, VCP/p97 re-expression in resistant melanoma cells completely restored immune recognition by Melan-A/MART-126-35 CTLs." (PMID 34576340, 2021). "All four known melanoma cell markers were candidate cell marker genes for cell type H, and MLANA, PMEL, and TYR were candidate cell marker genes for cell type G. In addition, the protein-coding gene PMEL was a candidate cell marker gene for five cell types (all cell types except C, D, and F)." (PMID 34784909, 2021). "Thus, isolated cells display specific phenotypical and functional features of melanocytes/melanoma cells such as tyrosinase and Melan-A expression and melanin production." (PMID 34944864, 2021). "Tumor cells exhibited markedly elevated expression of MLANA, a widely used biomarker of melanoma." (PMID 33424867, 2020). "Tumors expressed the differentiated melanoma cell markers, Melan-A and M-CAM." (PMID 32423311, 2020). "Melanoma cells were identified by expression of marker MELAN-A (MLANA)." (PMID 33182777, 2020). "Moreover, the proportion of differentiated effector-memory EM28neg Melan-A-specific T-cell subset was highly variable among the treated melanoma patients." (PMID 31969886, 2019). "In this study, we addressed the question whether the dose of Melan-A peptide and of CpG-B adjuvant used for therapeutic vaccination of melanoma patients can influence the in vivo expansion, differentiation, avidity, and function of the responding CD8 T-cells." (PMID 31969886, 2019). "Interestingly, one study reported the presence of two T cell clones with different affinities in Melan-A-specific TILs in human melanoma." (PMID 31379886, 2019). "Here we analyzed human cytotoxic CD8 T cells specific for the melanoma antigen Melan-A/MART-1." (PMID 31555299, 2019). "Since we observed a close correlation between the Wnt3a-CM or PKF115–584 treatment and the expression of pigmentation related genes (DCT, TYR, TYRP1, MITF) in our SKMEL28 microarray data, we analyzed the TCGA melanoma RNAseq expression data concerning MLANA expression." (PMID 29454361, 2018). "Additionally, we were able to show the presence of melanoma-specific markers (Melan-A and S100) in both cell lines, confirming the melanocytic origin of these malignant cells." (PMID 30514258, 2018). "In previous studies, it has been documented that the specific immune response against melanoma is dominated by two vast T cell repertoires specific for the melanoma antigens Melan-A and MELOE-1, which can be selected and amplified from the peripheral blood of HLA-A2 melanoma patients." (PMID 30214446, 2018). "Melanoma-specific antigens melan-A, S-100, and HMB45 were detected by immunohistochemical staining." (PMID 29197361, 2017). "The cell line exhibits well known melanoma markers such as Melan-A, S-100, Tyrosinase, and HMB-45." (PMID 28522871, 2017). "However, significant amounts of MYSM1 were detectable in the nuclei of Melan-A-positive melanoma cells in all 10 human superficial spreading melanoma (SSM) samples tested (third panel, representative sample)." (PMID 28978033, 2017). "Our experiments show that co-cultivation of the melanoma UKRV-Mel-15a and Ma-Mel-63a cells with Melan-A/MART-126-35 CTL led in both instances to the isolation of several melanoma cell clones, which revealed impaired presentation of the Melan-A/MART-126-35 antigenic peptide." (PMID 27143649, 2016). "We have previously shown that subcutaneous vaccination of stage III–IV melanoma patients with the mixture of Melan-A peptide, CpG-containing oligodeoxynucleotide, and Montanide induces large numbers of circulating Melan-A-specific CD8+ T cells in the majority of patients treated." (PMID 28018343, 2016). "Here, we show that short-term co-culture of Melan-A/MART-1 tumor antigen-expressing melanoma cells with Melan-A/MART-126-35-specific cytotoxic T lymphocytes (CTL) led to resistance against CTL-induced lysis because of impaired Melan-A/MART-126-35 epitope processing." (PMID 27143649, 2016).
melanoma (continued). "The expression of p97/VCP is not induced by cytokines and it is not clear at the moment why its expression may be so influenced by exposure of melanoma cells to Melan-A/MART-126-35 CTL." (PMID 27143649, 2016). "In those cases of ESFTs which display focal positivity for S100 or desmin, additional immunohistochemical stains for melanoma markers (HMB45, Melan-A) and specific skeletal muscle markers (myogenin, myoD1) can be utilized to exclude melanoma and rhabdomyosarcoma." (PMID 27413360, 2016). "Indeed, our cDNA array analyses of melanoma cells resistant to cytolysis by Melan-A/MART-126-35-specific CTL revealed several of the known ERAD components to be down regulated in these cells." (PMID 27143649, 2016). "Positive staining for S100, HMB-45, and Melan-A is characteristic of melanoma." (PMID 27814751, 2016). "We therefore decided to apply only two rounds of CTL co-culture for the selection of resistant melanoma clones, because under these conditions the HLA-A*0201 and Melan-A/MART-1 expressions of the surviving clones was similar or even higher than those of the parental UKRV-Mel-15a cell line." (PMID 27143649, 2016). "In addition, the tumor cells showed positive immunostaining for three melanoma markers, S-100, melan-A and HMB-45." (PMID 25624894, 2015). "We also note than MLANA mRNA serves as an excellent positive biomarker in peripheral blood from early stage melanoma patients, where it could represent circulating MTFs." (PMID 26267609, 2015). "SKMEL-28, OCM1a and other established melanoma cell lines had large cells easily discernible using hematoxylin and eosin stain, or Wright-Giemsa stain and by immunocytochemistry using Melan-A staining." (PMID 24811334, 2014). "Indeed, a previous study highlighted the EMT-like phenotypic switch in melanoma as a method of escape from adoptive T cell therapy with T-lymphocytes targeting Melan-A." (PMID 25566505, 2014). "Additionally, Western blot analyses showed exosomes positive for the melanoma-specific marker Melan-A, indicating that the liver perfusate exosomes are of tumour origin." (PMID 25510783, 2014). "Furthermore, exosomes stained positive for the melanoma-specific marker Melan-A, suggesting a tumour origin for at least a portion of the exosomes investigated." (PMID 25510783, 2014). "Here we explored the efficacy of computational design with the clinically relevant TCR DMF5, which recognizes nonameric and decameric epitopes from the melanoma-associated Melan-A/MART-1 protein presented by the class I MHC HLA-A2." (PMID 24550723, 2014). "However it showed strong positivity for the melanoma marker S-100 protein, and patchy staining for Melan-A and HMB-45 (Human Melanoma Black)." (PMID 25205351, 2014). "Therefore it must be observed in combination with a positive expression of HMB-45 and melan-A for the diagnosis of primary melanoma of the breast." (PMID 24959253, 2014). "We addressed these concerns by careful evaluation of lymph node preparations from melanoma and non-melanoma patients using a second melanoma-associated antibody directed against Melan-A and by genetic analysis of the gp100-positive cells." (PMID 24558354, 2014). "A valuable marker could be the melan-A/MART-1 (A 103) melanoma antibody, which is positive in all Leydig and in many Seroli-cell tumors, but negative in GCTs." (PMID 24894598, 2014). "S100B and Melan-A proteins are present in melanocytes and most melanomas." (PMID 24811334, 2014). "Microscopic examination demonstrated extensive Barrett esophagus with high-grade dysplasia as well as a second tumor which was morphologically different from the surrounding high-grade dysplasia and which was positive for S-100, HMB 45 and Melan-A on immunohistochemistry, consistent with melanoma." (PMID 24220097, 2013). "Likewise, HMB-45, a melanoma marker, also stained epithelial cells but to a lesser extent than melan-A." (PMID 23356913, 2013). "Melanoma samples were immunostained for the melanocyte specific target, Melan-A." (PMID 23690928, 2013).
melanoma (continued). "The B16.F10 cells showed weak expression of the melanoma marker Melan-A." (PMID 23614029, 2013). "Again, melanoma cells grown on matrices preconditioned by human embryonic stem cells “induced melanoma spheroid formation, promoted the re-expression of Melan-A, and inhibited melanoma cell invasion”." (PMID 24244914, 2013). "Recently, Melan-A has been widely used in the diagnosis of melanomas." (PMID 23476846, 2013). "Furthermore, Melan-A-specific T-cells in melanoma patients before vaccination also closely resembled total naive T-cells and Melan-A-specific T-cells from healthy donors." (PMID 22347406, 2012). "Given the apparent aberrant expression of typical melanocytic differentiation markers (such as TYR, MLANA), we chose to stain potential melanoma CTCs for pan-KRT, which is generally expressed in melanomas and has prognostic significance (particularly KRT18; see Discussion)." (PMID 22829910, 2012). "Melanoma tumor cells are stained with Melan-A and also with HMB45 and S-100." (PMID 21722390, 2011). "Other features include expression of another melanoma-associated antigen melan A, coexpression of muscle cell markers without cytokeratin expression and the presence of melanosomes or pre-melanosomes." (PMID 21846376, 2011). "To clarify this issue, we analyzed several HLA-A2/Melan-A-specific clonotypes derived from 40 melanoma patients and we compared their features with those found in 103 other individuals including 8 subjects of Ctrl/M-A group, 36 of Mel/noM-A group and 59 of Ctrl/HLA-A2+ group." (PMID 19317896, 2009). "The tumor cells also stained positive for NSE while the other melanoma associated marker, Melan A was negative." (PMID 17631685, 2007). "Recently, Appay and coworkers published their results on six patients with advanced melanoma treated with lymphodepleting chemotherapy with busulfan and fludarabine, followed by reinfusion of Melan-A specific CD8+ T cell containing peripheral blood mononuclear cells and Melan-A peptide vaccination." (PMID 17868452, 2007). "The discriminatory immunostaining pattern with the 'MCW Melanoma Cocktail' (a mixture of MART-1 {1:500}, Melan- A {1:100}, and Tyrosinase {1:50} monoclonal antibodies) allows intraoperative immunocytochemical evaluation of imprint smears of SLNs for melanoma metastases." (PMID 16999866, 2006). "Specifically, SOX10 has demonstrated greater expression stability compared to S100 in melanoma diagnostics, while Melan-A may be negative in amelanotic variants, highlighting the need for panel-based interpretation rather than reliance on individual markers." (PMID 41002705, 2025). "Interestingly, up to 22% of cases may express the melanocytic marker melan-A, with rarer expression seen of human melanoma black (HMB-45)." (PMID 39206137, 2024). "In addition, Melan-A has a higher sensitivity of 95% and specificity of 97% in melanomas." (PMID 39280438, 2024). "Also, Melan A-specific T cell clones in some cases represent predominant population in melanoma TILs and are present at high frequency in melanoma-infiltrated lymph nodes." (PMID 35377314, 2022). "The identification of ADAM10 as an MITF target gene, suggests that MITF may play a dual role in shaping the anti-melanoma immune response, both promoting expression of antigens like MLANA known to elicit a robust T-cell response, but at the same time suppressing NK-cell-mediated killing." (PMID 33789714, 2021). "Since expression of MLANA, a differentiation-associated melanosomal protein, is regulated by MITF, our results suggested that irradiation might also induce MITF expression, and that MITF could play a role in immune recognition of melanoma cells." (PMID 33789714, 2021). "Additionally, we reported a GH-induced upregulation and GHRKD-induced suppression of MITF-regulated melanogenesis pathway genes—TYR, TYRP1, TYRP2/DCT—as well as melanosomal markers PMEL (gp100) and MLANA, in multiple melanoma cell lines, xenograft models, and in silico analyses." (PMID 31547367, 2019).